MIR4670 (microRNA 4670)
Synonyms: hsa-mir-4670
Gene: MicroRNA gene on chromosome 9 (92,527,984 to 92,528,058, reverse strand). Ensembl gene ENSG00000264158.
Homologues: Orthologues: chimpanzee MIR4670 (100% identical).